HIF1A (hypoxia inducible factor 1 subunit alpha)
Diseases named in the same sentence as HIF1A in open-access papers (continued):
Sharing a sentence is not in itself a finding about the gene and the disease.
asthma (continued). "Furthermore, the cross-talking of the IL-4/13 signaling pathway and networks intermediated by transcription factor HIF-1α and FOXA1 play a crucial role in the pathogenesis of asthma." (PMID 31430856, 2019). "MBD2 and HIF-1α genes were silenced or overexpressed through lentiviral transduction to explore the roles of MBD2 in Th17 cell differentiation and IL-17 release in neutrophils-dominant asthma." (PMID 30150897, 2018). "Inhibition of HIF-1α expression can reduce airway inflammation and remodeling, suggesting that HIF-1α may be involved in the pathogenesis of asthma." (PMID 30150897, 2018). "In our study, HIF-1α expression increased in mouse splenic CD4+ T cells and lung tissues in both the neutrophils-dominant asthma and conventional asthma groups, but this was more significant in the neutrophils-dominant asthma group." (PMID 30150897, 2018). "Recently, HIF-1α has been demonstrated to be responsible for LPS-induced IL-1β expression in bone marrow derived macrophages; furthermore, HIF-1α activation has been shown to be correlated with chronic diseases such as asthma." (PMID 23935964, 2013). "As for asthma pathogenesis, numerous studies have indicated that PI3K/Akt modulates AHR, airway inflammation, and vascular permeability through the regulation of VEGF expression mediated by HIF-1α activity." (PMID 24312355, 2013). "Furthermore, mechanical strain of airway smooth muscle induces HIF-1α-dependent VEGF expression via mTOR and ERK pathways, which may thereby contribute to angiogenesis in asthma." (PMID 22685525, 2012). "Enhanced levels of HIF-1α, 2α and VEGF have been identified in lung tissues and bronchial epithelial cells of asthmatic patients as well as in the bronchial lavage of asthmatic patients, where they were associated with elevated levels of eosinophil counts as compared to persons without asthma." (PMID 22823210, 2012). "However, it has recently also been reported that mice lacking ARNT/ HIF-1α signalling in myeloid cells have increased allergic response in both a house dust mite model and an OVA murine asthma model, which may be driven by decreased IL-10 production." (PMID 31800592, 2019).
cardiac hypertrophy (52 papers, 2012 to 2026). "CA4 and HIF‐1α are associated with cardiac hypertrophy, whereas SIRT2 is negatively associated with hypertrophic cardiac disease." (PMID 40898929, 2026). "CCND1 has been implicated in the regulation of the cell cycle and cardiac hypertrophy in HF, and HIF1A is known to be involved in angiogenesis and tissue remodeling under hypoxic conditions, both of which are essential processes in HF progression." (PMID 40818967, 2025). "A study in children and adolescents with HCM particularly showed an association between Hif-1α activating SNPs and increased myocardial hypertrophy and diastolic dysfunction." (PMID 39820339, 2025). "Accordingly, changes associated with cardiac hypertrophy, such as HIF1α activation and hyperosmolality, were observed in both the FC and FF dams." (PMID 39335874, 2024). "Abnormal myocardial glucolipid metabolism is often associated with an increase in HIF-1α in hypertension-induced cardiac hypertrophy." (PMID 39416904, 2024). "Current evidence suggests that abnormal glycolipid metabolism and overexpression of HIF-1α in cardiac cells causes cardiac hypertrophy." (PMID 35495935, 2022). "Insulin/IGF1 and HIF1α are the components of key signaling mechanisms that regulate ROS levels associated with aging and cardiac hypertrophy and failure." (PMID 31511561, 2019). "The development of myocardial hypertrophy transiently causes hypoxia and HIF1α accumulation, leading to the initiation of angiogenesis." (PMID 25803693, 2015). "Notably, NPPA, enriched in DCM, HCM and HIF-1α pathways, encodes atrial natriuretic peptide, which promotes vasodilation and natriuresis to counteract cardiac hypertrophy." (PMID 40597665, 2025). "Hypoxia is a key regulator of cardiac hypertrophy and hypoxia also induces hypoxia-inducible factor 1-alpha (HIF1A) that in turn induces alternative splicing." (PMID 40382596, 2025). "Endothelium specific Hif-1α knockout aggravates cardiac hypertrophy and increase the LV/body mass ratio, whereas endothelium specific Hif-2α knockout was protective." (PMID 39820339, 2025). "In another study, a comprehensive analysis of transcriptomic data from HF patients and animal models revealed several key genes, such as MYC, CCND1, and HIF1A, which were found to play central roles in regulating cardiac hypertrophy and fibrosis." (PMID 40818967, 2025). "In rats with renovascular hypertension-induced cardiac hypertrophy, oral administration of 50–100 mg/kg of apigenin for 4 weeks led to decreased myocardial HIF-1α protein expression." (PMID 39416904, 2024). "CGA-enriched chrysanthemum extract (CME) prevents myocardial hypertrophy by targeting HIF-1α and PPARα pathways in rats with renal hypertension and H9C2 cells with stimulation of ANG II-hypoxia." (PMID 38612964, 2024). "CGAs can regulate NF-κB and PPARα pathways, lower HIF-1α expression, and suppress cardiac apoptotic signaling, thus executing beneficial effects against cardiac hypertrophy and heart failure (HF)." (PMID 38612964, 2024). "We compared these changes to changes observed in the human cardiac tissue and saw decreased mitochondrial metabolic activity and increased HIF1α activity, cardiac hypertrophy signaling, and pro-inflammatory changes comparable to those in the tissue cells." (PMID 38776872, 2024). "These evidences suggest that HIF-1α plays a significant role in the process of MI and pathologic cardiac hypertrophy by regulating RNA alternative splicing." (PMID 39045460, 2024). "Curiously, HIF1α also regulates fructose metabolism, and it is known that fructolysis supports anabolic growth that promotes cardiac hypertrophy." (PMID 39335874, 2024). "In several vivo studies, Hif1a participated in maintaining the vascular density within the myocardium and prevented pressure-induced cardiac hypertrophy and HF." (PMID 37609434, 2023). "In human tissues and in mouse models of cardiac hypertrophy induced by aortic constriction, HIF-1α levels increased." (PMID 37175562, 2023).
cardiac hypertrophy (continued). "In human and mouse models of cardiac hypertrophy, glycolytic metabolism is turned on due to increased HIF-1α." (PMID 37175562, 2023). "Cardiac-specific deletion of HIF1α in mice has been shown to prevent the metabolic switch and cardiac hypertrophy." (PMID 35575090, 2022). "This further suggests that hyperactivation of HIF1α signaling resulting from neutrophil KLF2 deficiency exacerbates inflammation and worsens cardiac hypertrophy." (PMID 34793333, 2022). "We find that upregulation of ATPIF1 triggers the metabolic switch via activation of HIF1α signaling in pathological cardiac hypertrophy." (PMID 35575090, 2022). "HIF1α is a powerful transcriptional stimulator of glycolysis, and its activation has been reported in pathological cardiac hypertrophy, but the upstream trigger of HIF1α activation is less clear." (PMID 35575090, 2022). "To further analyse the therapeutic effect of SMY on myocardial hypertrophy in rats, we assessed the expression of HIF1α/PPAR signalling pathway-related proteins." (PMID 36118100, 2022). "Previous studies have also shown that the HIF-1 signaling pathway plays a role in cardiac hypertrophy, and the knockdown of HIF-1α attenuated HIMF-induced cardiomyocyte hypertrophy." (PMID 36157891, 2022). "Myocardial hypoxia enhances fructose metabolism in human and mouse models of pathological cardiac hypertrophy through HIF-1α activation of SF3B and SF3B1-mediated splice switching of KHK-A to KHK-C." (PMID 32069878, 2020). "Clearly the role of endothelial HIF-1α in the pathogenesis of cardiac hypertrophy deserves further attention." (PMID 32733885, 2020). "Earlier studies have revealed that IGF-1/HIF1α pathway is activated during iron overload and ROS burst, in cardiac hypertrophy and aging conditions." (PMID 31511561, 2019). "Cardiac-specific overexpression of HIF-1α has been shown to prevent deterioration of the cardiac glycolytic pathway, restore ATP production, and ameliorate cardiac hypertrophy in diabetic mice." (PMID 31597394, 2019). "HIF1α activation of SF3B1-dependent splicing of KHK enforces fructolysis to promote cardiac hypertrophy in response to pathologic stress." (PMID 29695975, 2018). "The decrease in cardiac HIF1α content in the resveratrol-treated mice indicates that the resveratrol-mediated decrease in cardiac hypertrophy decreases the need for increased vascularization." (PMID 24936291, 2014). "HIF-1α stabilization under hypoxia allows the transcription of genes and processes to modulate physiological adaptation during HH, however, its sustained signaling becomes detrimental as it worsens inflammation, fibrosis, and cardiac hypertrophy." (PMID 40108505, 2025). "While individual studies have shown that CCND1 and HIF1A are crucial players in cell proliferation and migration, particularly in cardiac hypertrophy and vascular remodeling, the interaction of these genes within the PI3K/AKT pathway in HF is still not fully understood." (PMID 40818967, 2025). "This hypothesis was based on several lines of evidence: First, a study on children and adolescents with HCM showed that upregulation of the Hif-1α correlated with increased cardiac hypertrophy and diastolic dysfunction." (PMID 39820339, 2025). "Additionally, 4-CQA attenuates LPS-induced inflammatory responses and oxidative stress and ameliorates myocardial hypertrophy through a hypoxia-inducible factor 1 subunit alpha-related pathway." (PMID 38718039, 2024). "Changes in glucose and lipid metabolism may be caused by the activation of HIF1α, which is a key regulator of glucose and lipid metabolism, and when myocardial hypertrophy occurs, myocardial hypoxia activates HIF1α." (PMID 36118100, 2022). "Collectively, these transcriptomic and genetic studies indicated that the KLF2/HIF1α axis is critical for AngII-induced neutrophil activation and cardiac hypertrophy, likely through the regulation of NETosis and resultant thrombosis in small vessels of the myocardium." (PMID 34793333, 2022).
cardiac hypertrophy (continued). "Previous studies found that NOX4 knockout mice exhibited severe cardiac hypertrophy and contractile dysfunction after pressure overload, whereas NOX4 transgenic mice showed enhanced angiogenesis and increased expression of VEGF and Hif1α as well as less cardiac hypertrophy after pressure overload." (PMID 34513812, 2021). "Therefore, we recommend a new molecular approach which illustrates that HSF1 and its target HIF‐1α/VEGF signalling pathway influences the exercise training‐activated cardioprotection against pressure overload–initiated cardiac hypertrophy." (PMID 31930683, 2020). "It is reasonable to speculate that mice with endothelial HIF-1α deficiency would phenocopy the BRG1 ecKO mice and develop attenuated cardiac hypertrophy when compared to the control mice." (PMID 32733885, 2020). "Also enriched in CB-EPCs are HIF1α (hypoxia-inducible transcription factor 1 alpha) signaling, cardiac hypertrophy signaling, renin-angiotensin signaling and NFAT in cardiac hypertrophy pathways, reflecting the pro-angiogenic nature of CB-EPCs." (PMID 22943456, 2012). "Furthermore, cardiac specific Hif-1α knockout is able to reverse pathological myocardial remodeling in the α-MHC719/+ mouse model as evidenced by decreased ventricular hypertrophy, myocardial fibrosis, diastolic dysfunction, oxidative stress, and cardiomyopathic RNA and protein profiles." (PMID 39820339, 2025). "Therefore, we concluded that SMY may ameliorate ISO-induced myocardial hypertrophy by regulating the HIF1a-PPAR pathway and the expression of downstream glycolipid metabolism-related proteins, thereby alleviating the disturbance of energy metabolism." (PMID 36118100, 2022). "In addition, the peroxisome proliferator-activated receptor γ (PPARγ) and HIF1α in human and mouse cardiac hypertrophy activated FAs uptake and GPL biosynthesis genes, and increased glucose-to-GPL conversion via G-3P pathway followed by changing myocardial metabolism and forming heart disease." (PMID 31316482, 2019). "The results show that SMYH can inhibit the protein expression of HIF1α/PPAR signalling pathway-related proteins and activate the PKA signalling pathway, thereby alleviating energy metabolism disorders in rats with myocardial hypertrophy." (PMID 36118100, 2022). "Under pathologic stress, HIF-1α activated PPAR-γ, which subsequently resulted in changes in energy metabolism and cardiac hypertrophy." (PMID 35833024, 2022). "Western blot analysis showed that SMY inhibited the protein expression of HIF1α/PPAR signalling pathway-related proteins to activate the PKA signalling pathway, thereby ameliorating energy metabolism disorder in rats with myocardial hypertrophy." (PMID 36118100, 2022). "HIF1α could also activate SF3B1, a splicing factor mediating isoform switch of ketohexokinase from KHK-A to KHK-C in pathologic cardiac hypertrophy." (PMID 39045460, 2024). "These HG-specific activated pathways include the proinflammatory interleukin-8 (IL-8) signalling, hypoxia-inducible factor-1alpha (HIF-1α) signalling, cardiac hypertrophy signalling (enhanced) and the role of nuclear factor of activated T-cells (NFAT) in cardiac hypertrophy." (PMID 36463298, 2022). "HIF-1α expression induced by pressure load will lead to a significant increase in heart mass to body weight ratio and increased BNP expression and promote the occurrence of myocardial hypertrophy." (PMID 36046382, 2022). "It was demonstrated that splice factors as HIF-1α targets, which prompted the analysis of their RNA targets, unveiling mechanistic and functional linkages between HIF-1α, splice factor 3b subunit 1 (SF3B1), KHK-C splice isoform production and fructose metabolism in cardiac hypertrophy." (PMID 32069878, 2020). "Experiments with the homozygous conditional deletion of HIF1-α, in smooth muscle cells, demonstrated that the deletion of HIF1-α can reduce pulmonary vascular remodeling and PH without affecting ventricular hypertrophy and cardiac remodeling." (PMID 32764403, 2020).
cardiac hypertrophy (continued). "One possible explanation for this apparent discrepancy is that regulation of MRP8 by HIF-1α does not represent the overarching function of HIF-1α in endothelial cells in the settings of cardiac hypertrophy." (PMID 32733885, 2020). "However, in the present study, we did not observe that HIF1α and fructose work in synergy inducing cardiac hypertrophy." (PMID 39335874, 2024). "Notably, high expression of Hif-1α promoted cardiac hypertrophy, and low expression of Hif-1α reduced the cross-sectional area of cardiomyocytes, suggesting that the pro-hypertrophic effect of HIF-1α is non-controversial." (PMID 36172572, 2022). "In this study, we did not detect the expression of HIF-1α and p-HIF-1α in vivo and the other cardioprotective effects of TMSB4OE-BMMSCs such as inflammation, immunity, myocardial hypertrophy, cell migration, and proliferation." (PMID 34178995, 2021). "Physical exercise did not induce cardiac hypertrophy, whereas it increased mRNA levels of the PGC-1α, HIF-1α and VEGF genes, which are involved in mitochondrial biogenesis and angiogenesis, and reduced mRNA levels of FoxO3a, MuRF-1 and Atrogin-1." (PMID 23922868, 2013). "Thus, stabilization of HIF-1α, but not TEAD1, may allow YAP to induce salutary actions even during chronic PO by inducing compensatory cardiac hypertrophy." (PMID 35133975, 2022).